LINC02082 (long independently transcribed non-coding RNA 2082)
Gene: Long non-coding RNA gene on chromosome 3 (168,864,902 to 168,924,590, forward strand). Ensembl gene ENSG00000242268.
Diseases named in the same sentence as LINC02082 in open-access papers:
LINC02082 is named in the same sentence as 4 diseases in open-access papers, as found by Europe PMC text mining. Sharing a sentence is not in itself a finding about the gene and the disease. The quoted sentences say what the papers report.
thyroid (1 paper, 2022). "Our previous study demonstrated that LINC02082 expression is elevated in human thyroid cancer, and it may play a critical role in thyroid carcinogenesis." (PMID 36132147, 2022).
thyroid nodule (1 paper, 2022). A small circumscribed mass in the THYROID GLAND that can be of neoplastic growth or non-neoplastic abnormality. "This indicates that the measurement of the expression levels of LRRC52-AS1, LINC02082, UNC5B-AS1, MPPED2-AS1, LNCNEF, and LOC100129129 could be used for differentiating between benign and malignant tumors in thyroid nodules." (PMID 36132147, 2022).
LINC02082 also shares sentences with these, for which no sentence is quoted: malignant tumors (1 paper); thyroid cancer (1).